CDK12 (cyclin dependent kinase 12)
Diseases named in the same sentence as CDK12 in open-access papers (continued):
Sharing a sentence is not in itself a finding about the gene and the disease.
breast carcinoma (continued). "CDK12 is highly active in these tumors, and it has been proposed as a druggable target in HER2-amplified breast cancer." (PMID 29090014, 2017). "Interestingly, we found in-frame fusions involving Cyclin Dependent Kinase 12 (CDK12) as a 3’ partner in three cell lines: MDA-MB-361, UACC-893 (both derived from breast carcinoma) and NCI-N87 (gastric carcinoma)." (PMID 41421967, 2025). "In addition, CDK12 synergizes with other oncogenes, such as HER2 in breast cancer, to promote tumorigenesis and metastasis." (PMID 40166687, 2025). "Notably, compared to the CDK12/13 inhibitor THZ531, the CDK12/13 degrader YJ9069 effectively inhibited cell proliferation in subsets of prostate and breast cancer cell lines preferentially over benign immortalized cells." (PMID 39353441, 2024). "Using data from breast and non-small cell lung cancers they identify several clinically relevant phosphorylation modules including a cell cycle checkpoint module enriched in basal breast cancer samples and a module of PRKC isozymes putatively co-regulated by CDK12 in lung cancer." (PMID 37394063, 2023). "To provide preclinical proof-of-concept of the therapeutic actionability of CDK12-induced SGOC metabolic alterations, we generated patient-derived xenografts (PDXs) from CDK12HIGH (Patients #1 and #2) and CDK12LOW (Patients #3 and #4) human breast cancers." (PMID 35550508, 2022). "Further evidence of the clinical value of CDK12 was provided by the analysis of three independent cohorts of luminal, TNBC and HER2-pos breast cancer patients treated in the neoadjuvant setting, where the mainstay pre-operative treatment is TaxAC-based therapy." (PMID 35550508, 2022). "In approximately 71% of HER2+ breast cancers, the HER2 amplicon also contains the CDK12 gene." (PMID 34686673, 2021). "Another oncogenic property of overexpressed CDK12 leads to the downregulation of the DNAJB6-L protein (via ALE splicing of its mRNA), which promotes the cell migration and invasiveness of HER2-positive breast cancer cells." (PMID 34316683, 2020). "Interestingly, CDK12 plays distinguishing roles among various subtypes of breast cancer, especially for HER2 (human epidermal growth factor receptor 2)-positive breast cancer and triple-negative breast cancer (TNBC)." (PMID 32570740, 2020). "It is shown that CDK12 and HER2 oncogenes are co-amplified in breast cancer." (PMID 32570740, 2020). "While minor risks for breast cancer cannot be excluded, our case-control analyses indicate that CDK12 c.1047-2A>G does not represent a clinically actionable mutation." (PMID 31259151, 2019). "The median age at diagnosis for CDK12 c.1047-2A>G carriers was 53.5 years (range 40–61 years) and none had a family history of breast cancer, although one of the six carriers had a first-degree relative with ovarian cancer." (PMID 31259151, 2019). "CDK12, LASP1, RAE1, C17orf57, NSF, and USH2A were partners of out-of-frame, but not in-frame, fusion genes here and in other massively parallel sequencing analyses of breast cancers 12,15–17,41–43." (PMID 24395524, 2014). "A significant reduction in CDK12 mRNA expression was observed in these cell lines relative to HER2-amplified breast cancer cell lines that did not harbour a breakpoint involving CDK12 (p = 0.0360, t-test)." (PMID 24395524, 2014). "Of the out-of-frame validated chimeras, we identified recurrent expressed chimeric transcripts involving CDK12 (2.7%) and RAE1 (1%), and DNA rearrangements involving C17ORF57 (0.5%), NSF (0.5%), USH2A (0.5%), and LASP1 (1%) from unselected breast cancers in external datasets 12,15–17,41–43." (PMID 24395524, 2014). "Interestingly, recent in vitro experiments showed that CDK12 drove trastuzumab resistance and treatment with a CDK12 inhibitor enhanced the sensitivity to anti‐HER2 therapy through the PI3K/Akt and Wnt pathways in breast cancer." (PMID 37325934, 2023).
breast carcinoma (continued). "Delivery of ICD inducers, such as SR-4835 (a CDK12/13-specific inhibitor), RIG-I agonists and chemotherapeutics, as well as photothermal agents, with synthetic nanoparticles, has been confirmed to have therapeutic potential in several preclinical models of breast cancer." (PMID 35148751, 2022). "We modeled CDK12 overexpression in the normal human mammary epithelium by enforcing CDK12 expression in the normal mammary epithelial MCF10A cell line (CDK12-OE MCF10A cells), obtaining CDK12 levels comparable to the breast cancer BT474 cell line that bears CDK12 overexpression." (PMID 35550508, 2022). "Indeed, a recent study showed a CDK12-dependent transcriptional upregulation of IRS1 and WNT ligands leading to the activation of oncogenic ERBB–PI3K–AKT and WNT signalling pathways in HER2-positive breast cancer." (PMID 34316683, 2020). "Additionally, a fusion form of the likely nonfunctional CDK12 gene was also found in a micropapillary breast cancer sample." (PMID 29090014, 2017). "However, CDK12 is not an independent predictor of breast cancer-specific survival." (PMID 32570740, 2020). "If high CDK12 activity has these functions, then how can HER2-positive breast cancer cells develop tumors without disrupting genome stability?" (PMID 32451425, 2020). "Whether in HR+ or HR− subtype, HER2-positive breast cancer was characterized by gains in 17q12 (ERBB2, CDK12, HNF1B, RAD51D), and almost no gains of 17q12 were present in the other subtypes." (PMID 37264417, 2023). "Cyclin-dependent kinase 12 (CDK12), located on chr17q12, has a high concurrent amplification rate similar to HER2 (about 90% of HER2+ breast cancers), and the results show that CDK12 enhances CSC self-renewal in breast cancer in a manner independent of HER2." (PMID 36276152, 2022).
ovarian carcinoma (57 papers, 2015 to 2025). A malignant neoplasm originating from the surface ovarian epithelium. "For instance, loss of CDK12 function occurs in 3–4% of patients with ovarian cancer and cause tandem duplications (TDs) that result in genomic instability." (PMID 39533070, 2025). "In sum, Cdk12 loss in murine ovarian cancer effectively recapitulates the immune response seen in human disease, and this can be studied in greater detail using 6137J-derived allografts as a model system." (PMID 40504161, 2025). "CDK12 is one of the most frequently mutated genes in ovarian carcinoma and these mutations lead to a loss of function." (PMID 40148269, 2025). "In fact, the CDK12 seemed to regulate genes involved in the DDR and thus controlled genomic stability and the loss of the CDK12 was described as a resistant mechanism to PARPi in ovarian cancer." (PMID 39351435, 2024). "For instance, in ovarian cancer, CDK12 loss downregulates transcripts in the HR DNA repair pathway—a phenotype attributed to reduced CDK12/cyclin K-mediated transcriptional elongation of the corresponding genes." (PMID 39368479, 2024). "In this line, CDK12 loss-of-function mutations in ovarian cancer cells sensitize the cancer cells to the effect of poly ADP-ribose polymerase (PARP) and CHK1 inhibitors." (PMID 38132164, 2023). "Mutations in CDK12 have been reported in different tumor types and it is one of the most mutated genes in ovarian carcinoma." (PMID 35912188, 2022). "On the other hand, CDK12 has been previously reported to be associated with altered PARPi response in ovarian cancer, and several studies reported synergistic effects on CDK12 inhibition with PARPi." (PMID 36307400, 2022). "Cyclin-dependent kinase 12 (CDK12) is also one of the only nine significantly mutated genes in ovarian cancer (3% of cases in the TCGA dataset) and is known to promote the transcription of several HR pathway genes, including BRCA1." (PMID 35052761, 2021). "By contrast, deletion and/or null mutations in CDK12 were reported in ̃ 5% of prostate and ovarian cancer patients, where this genetic alteration is correlated with worse prognosis, thus indicating a putative tumour suppressor role for CDK12 in these cancers." (PMID 34092037, 2021). "Somatic CDK12 mutations or chemicals that disable CDK12 function in ovarian cancer cells reduce BRCA1 levels, disrupt HR repair, and sensitize these cells to platinum." (PMID 34645978, 2021). "Ovarian carcinomas with CDK12 loss have reduced expression of multiple HRGs, and CDK12 loss is reported to exhibit synthetic lethality with PARPi, though early results of PARPi in CDK12-mutant mPC have identified few responses." (PMID 34877933, 2021). "The study reported that the loss of CDK12 in ovarian cancer cells increased sensitivity to Olaparib treatment." (PMID 32235451, 2020). "CDK12 mutations are frequently found in aggressive breast and ovarian cancers, while loss of CDK12 function results in abnormal expression of DNA damage response genes and genome instability." (PMID 32451425, 2020). "More importantly, CDK12 LOF genomic alterations are associated with focal tandem duplications (FTDs) in ovarian cancer." (PMID 32570740, 2020). "A c.1047-2A>G splice site variant of the CDK12 gene was recently reported to strongly associate with hereditary breast and ovarian cancer in patients of Tatar ethnic origin." (PMID 31259151, 2019). "We tried to explore the functional consequence of the selected polymorphism on CDK12 mRNA expression level, as recently has been published on the predictive role of CDK12 mRNA level in OS of ovarian cancer patients." (PMID 27905519, 2016). "Given this background, we wanted to explore the role, if any, of CDK12 polymorphism in treatment response in ovarian cancer patients." (PMID 27905519, 2016). "A study has shown that CDK12-deficient ovarian cancer cells are more sensitive to Veliparib compared to their controls." (PMID 27642590, 2016).
ovarian carcinoma (continued). "We here report the retrospective analysis of polymorphisms in 5 genes (ATM, ATR, Chk1, Chk2 and CDK12) involved in the cellular response to platinum in a cohort of 240 cancer patients with late stage ovarian cancer." (PMID 27905519, 2016). "Hypothesizing it also had tumor suppressor function in HGSC, we compared gene expression in CDK12-mutated cases with control cases using The Cancer Genome Atlas (TCGA) ovarian cancer dataset." (PMID 40504161, 2025). "Furthermore, ovarian cancer patients harbouring deletions of either CDK12 or CDK13 also carry mutations in at least one other DDR gene, supporting the idea that loss of CDK12/13 is associated with higher tumour mutation burden." (PMID 39533070, 2025). "Moreover, novel deleterious mutations in the kinase domain of CDK12 (H857Y/R, F8787S, T893I) have been identified in ovarian cancer patients." (PMID 40148269, 2025). "As such, aberrant expression of RNA splice factors such as SRSF3 is associated with ovarian cancer, and we find that Drp1(-/17) is more strongly expressed in tumors with documented CDK12 mutations, a cyclin-dependent kinase that has been associated with regulation of the spliceosome." (PMID 39191946, 2024). "It has been recently demonstrated that ovarian cancers with inactivating mutations of CDK12 present genomic instability characterized by hundreds of tandem duplications of up to ten megabases (MB) in size (CDK12 TD-plus phenotype)." (PMID 35912188, 2022). "CDK12 is one of the most mutated genes in ovarian carcinoma." (PMID 35912188, 2022). "A genome-wide synthetic lethal screen involving ovarian cancer cell lines and olaparib determined that CDK12 deficiency may confer sensitivity to PARPis." (PMID 33233320, 2020). "This provides evidence that CDK12-deficient ovarian cancers could be targets for PARP inhibitor therapy, and further work should be done to evaluate PARP inhibitor efficacy in other CDK12-deficient tumors." (PMID 27642590, 2016). "Thus, we also asked whether there is a correlation between MYC amplification and the mutational status of the CDK12/13 genes in ovarian cancer." (PMID 37202753, 2023). "Meanwhile, loss-of-function of CDK12 is a common correlation with TD phenotype and increases T lymphocyte infiltration, leading to sensitization of cancer cells to some immune checkpoint inhibitors, such as antiprogrammed cell death-1 (PD-1) in prostate and ovarian cancers." (PMID 33628849, 2021). "In addition, the mutation frequencies of BRCA2 and CDK12 were significantly higher in the C2 subtype than in the other two subtypes, suggesting that mutation of DNA repair-related genes significantly affects the prognosis of ovarian cancer patients." (PMID 34222009, 2021). "For example, loss of CDK12/cyclin K-mediated transcriptional elongation of genes in the HR DNA repair pathway, including BRCA1, has previously been demonstrated in ovarian cancers." (PMID 40504161, 2025). "Taken together, our work, therefore, defines Cdk12 as a bona fide tumor suppressor gene in both prostate and tubo-ovarian cancer." (PMID 40504161, 2025). "Together, the findings establish Cdk12 as a tumor suppressor gene in ovarian cancer and define a novel treatment strategy with potential therapeutic relevance in CDK12-mutant HGSC." (PMID 40504161, 2025). "Taken together, these data demonstrate that CDK12 loss increases dependence on CDK13, rendering ovarian cancer cells sensitive to CDK13/12 degraders." (PMID 40504161, 2025). "Human prostate and ovarian cancers with biallelic CDK12 inactivation develop T cell–predominant lymphocytic infiltrates." (PMID 40504161, 2025).
ovarian carcinoma (continued). "Primary PRN;Cdk12KO cell lines represent a system amenable to preclinical testing of precision therapeutics for CDK12-inactive ovarian cancer." (PMID 40504161, 2025). "Here, a combination strategy comprising Olaparib and CDK12-IN-3 effectively inhibited the growth of HR-proficient ovarian cancer in cell line, patient-derived organoid (PDO), and mouse xenograft models." (PMID 39247812, 2024). "In this study, a novel CDK12 inhibitor, CDK12-IN-3, when cooperates with Olaparib, leads to fierce growth retardation of ovarian cancer cells in vitro and in vivo." (PMID 39247812, 2024). "Among the CDK12/13-targets involved in transcription, PAX8 is a well-established diagnostic marker of ovarian cancer." (PMID 37202753, 2023). "For example, we identified in the HMF breast metastasis series significantly recurrent mutations of CDKN1A (known driver in bladder cancer), MAX (known in paragangliomas, endometrioid and colon carcinomas) and CDK12 (known in ovarian cancer)." (PMID 36937541, 2023). "To understand CDK12’s role in tumor growth and response to therapy better, we here generated ovarian cancer cells knocked out for CDK12." (PMID 35912188, 2022). "Recently, we reported that CDK12 mRNA levels were predictive of platinum response in a xenobank of patient-derived ovarian carcinomas." (PMID 35912188, 2022). "The deregulations of CDK12 induces tumorigenesis via DNA repair defects in ovarian cancer, such as inactivation of the homologous recombination (HR) repair pathway." (PMID 32489449, 2020). "Consistent with a role in genome stability, CDK12 was identified as a likely tumor suppressor for ovarian cancer several years ago, and evidence continues to accumulate linking CDK12 alterations to ovarian and other types of cancer." (PMID 31652541, 2019). "Increased sensitivity of CDK12-compromised cells to cisplatin, the alkylating agent melphalan, and the PARP1 inhibitor veliparib was observed in a CDK12-silenced ovarian cancer cell line." (PMID 29090014, 2017). "Ovarian cancer cell lines with lower expression of CDK12 are more sensitive to olaparib treatment, and downregulation of CDK12 leads to increased olaparib sensitivity." (PMID 29090014, 2017). "Furthermore, though CDK12 inactivation in the Skov3 ovarian cancer cells showed some preferential downregulation of long genes overall, BRCA1 and BRCA2 protein were not affected." (PMID 39071291, 2025). "We then employed human OVCAR8 ovarian cancer cells to determine whether CRISPR-based CDK12 ablation also conferred sensitivity to CDK13/12 degrader therapy." (PMID 40504161, 2025). "We then tested whether pharmacologically targeting CDK13 preferentially killed Cdk12 KO ovarian cancer cells." (PMID 40504161, 2025). "Moreover, these kinases were shown to cooperate also in ovarian cancer cells, further suggesting that dual CDK12/13 inhibition is required to block their oncogenic functions in HGSOC." (PMID 37202753, 2023). "Our method is able to identify the known cancer drivers and further nominate candidates that exhibit higher breakpoint proximity than expected by random chance, such as DMD and LRRN3 in esophageal cancer, NF1 in ovarian cancer, CDK12 in uterine cancer, and WWOX in colorectal cancer." (PMID 36163358, 2022). "Overall, since multiple PARPi have been approved for clinical use in breast and ovarian cancers with BRCA1/2 mutations, CDK12 mutations could be used as other biomarkers for their application." (PMID 34316683, 2020). "In addition, BRCA1 promoter hypermethylation or mutational inactivation of CDK12 can downregulate transcription of BRCA1, thereby disrupting HR DNA repair in ovarian cancer, and then leading to metabolic reprogramming of ovarian cancer cells." (PMID 32570740, 2020).